MEIS1 (Meis homeobox 1)
Diseases named in the same sentence as MEIS1 in open-access papers (continued):
Sharing a sentence is not in itself a finding about the gene and the disease.
tumor (64 papers, 2004 to 2026). "ELF1 has been implicated in transcription regulation of several tumor-promoting genes including Tie2, MEIS1, CCL2, LUCAT1." (PMID 32795319, 2020). "Our findings that the MEIS1–HOXB13 complex is crucial to maintain the tumor-suppressing function of MEIS1 portray these mutations in a new light." (PMID 32553107, 2020). "BRAFp.V600E was the only significant variable associated with MEIS1 promoter methylation, after adjustment for tumor location and MSI status (Adjusted OR = 10.2, CI = 3.7 - 27.7, P < 0.000001)." (PMID 24244575, 2013). "The frequency of MEIS1 methylation in BRAFp.V600E mutated tumors was 60% for the consecutive cohort and 50% for the epithelial fractions of flow-sorted tumor samples." (PMID 24244575, 2013). "The inferred activity of the transcription factors MEIS1/2 was associated with both the mesenchymal- and the neuroepithelial-like undifferentiated tumor cell populations, thus representing a potential candidate for the development of therapies that simultaneously target both populations." (PMID 35803925, 2022). "Depletion of Meis1 and Meis2 in vivo may cause tumor growth and an increase in the expression of protumorigenic genes c-Myc and CD142." (PMID 33402862, 2020). "Higher level of MEIS-1 in tumor tissue is associated with better RFA treatment outcomes." (PMID 29632641, 2018). "MEIS1 functions as a tumor suppressor to inhibit CRC cell growth and tumor formation by suppressing DNA damage repair and increasing the sensitivity to oxaliplatin." (PMID 38478147, 2025). "Conversely, among the four downregulated genes (KANK2, SGCA, SLC12A4, and MEIS1), higher expression correlated with better prognosis, suggesting their potential tumor-suppressive roles." (PMID 40525903, 2025). "As a transcription factor, MEIS1 drives cell growth, dysregulated MEIS1 expression contributes to tumorigenesis in multiple tumor types." (PMID 36836180, 2023). "Meis1 is expressed in different solid tumors and is involved in the proliferation and differentiation of tumor cells." (PMID 36952432, 2023). "IHC revealed that the ratio of Ki67-positive cells was negatively correlated with intracellular MEIS1 protein level, which supported that MEIS1 indeed impeded tumor growth." (PMID 35351858, 2022). "In vivo assay indicated that the effect of ELFN1-AS1 on tumor growth depends on its negative regulation of MEIS1, verified and supported by detecting these mRNA and protein levels derive from xenograft tumor samples." (PMID 35351858, 2022). "MEIS1 transcriptionally regulated the expression of hypoxic tumor markers, namely Hif-1α and Hif-2α, which had crucial roles in tumorigenesis." (PMID 33776902, 2021). "In brief, Meis1 and Prep1 require Pbx in their respective tumorigenic or tumor suppressive functions and target the same molecular pathways, but in the opposite way." (PMID 34698191, 2021). "Upregulation and activation of Syk by Meis1 has been identified as a key regulatory mechanism in a Hoxa9/Meis1-driven tumor in a mouse model." (PMID 34698191, 2021). "Integration of ChIP-seq and RNA-seq data revealed direct and HOXB13-dependent regulation of proteoglycans including decorin (DCN) as a mechanism of MEIS1-driven tumor suppression." (PMID 32553107, 2020). "Both the tumorigenic activity of MEIS1 and the anti-tumorigenic activity of PREP1 require the interaction with the cofactor PBX4, which thus acts as an oncogene or as a tumour-suppressor, depending on its partner, MEIS1 or PREP1." (PMID 33033354, 2020). "The HOXB13-dependency of MEIS1 tumor suppressive function in PrCa cells was further demonstrated with the analyses of cell migration phenotypes." (PMID 32553107, 2020). "RNAi screening in MPNST cells revealed that Meis1 is an important factor (functioning as a potent oncogene) for MPNST tumor development." (PMID 33402862, 2020).
tumor (continued). "Prior studies implicated MEIS1 and MEIS2 as putative tumor suppressors in PrCa based upon clinical associations between retention of tumor expression and overall survival or risk of metastasis." (PMID 32553107, 2020). "In particular, overexpression of PREP1 inhibits the growth of MEIS1-dependent tumour cells, competing in vivo for the MEIS1 DNA-binding sites." (PMID 33033354, 2020). "To identify direct gene targets and pathways regulated by MEIS1 in prostate cells and identify mechanisms of tumor suppression, we performed chromatin immunoprecipitation and sequencing (ChIP-seq) of MEIS1 in the CWR22Rv1-LV-MEIS1 line." (PMID 32553107, 2020). "It was reported that MEIS1 expression has an inverse correlation with lymph node involvement and tumor stage in ESCC." (PMID 31470870, 2019). "Here we have sought to investigate the significant changes in expression level of some gene related to tumor cell differentiation following MEIS1 silencing in ESC cell line KYSE‐30." (PMID 31090196, 2019). "Numerous TFs including PREP1, HOXA7, HOXA9, and CREB1 regulate MEIS1 expression in different normal tissues and several tumor cells (Torres‐Flores, 2013)." (PMID 31090196, 2019). "We observed that overexpression of MEIS-1 reduced tumor growth, and the RFA treatment resulted in shrinkage of the tumors." (PMID 29632641, 2018). "Overexpression of MEIS-1 enhanced the efficiency of RFA’s anti-tumor effect on HCC cell proliferation in vivo." (PMID 29632641, 2018). "Overexpression of MEIS-1 enhanced the tumor rejection effect of RFA in preventing subcutaneous growth of HCC cells." (PMID 29632641, 2018). "In these studies, the authors proposed that MEIS-1 inhibits tumor cell proliferation and induces cell cycle arrest." (PMID 29632641, 2018). "In this study, we find that MEIS1 is less expressed in some ccRCC cell lines and ccRCC specimens than in non-tumor kidney cells and specimens." (PMID 28270206, 2017). "Tumor profiling and ChIP-sequencing data in a genetically-defined set of cell lines show that: 1) The number of Meis1 and Prep1 DNA binding sites increases linearly with their concentration resulting in a strong increase of “extra” target genes." (PMID 26259236, 2015). "With these caveats, we consider the genes bound and overexpressed by Meis1 in M cells as potentially tumorigenic and those by Prep1 in MP cells as potentially tumor suppressive." (PMID 26259236, 2015). "Homeobox genes such as Meis1 (myeloid ecotropic insertion site 1) are known to play a crucial role in normal development and tumor development." (PMID 25013928, 2014). "Here, we present knockout and cell marker studies revealing Meis1’s roles in both normal and tumor development." (PMID 25013928, 2014). "Instead of being localized to the stem cell region, Meis1 is localized to more differentiated cells in tumor tissues." (PMID 25013928, 2014). "In contrast, our studies in the two-stage skin carcinogenesis mouse model indicate that Meis1 function changes to a more pro-tumorigenic role, supporting tumor development and malignant conversion." (PMID 25013928, 2014). "Using flow-sorting, we detected MEIS1 promoter methylation both in the epithelial tumor fractions as well as in the normal stromal fractions." (PMID 24244575, 2013). "In a recent study, the truncated transcription variant of MEIS1, MEIS1D27, showed decreased expression in the proximal colon, suggesting a tumor suppressor function." (PMID 24244575, 2013). "Four out of eight BRAFp.V600E tumor epithelial fractions (50%) showed MEIS1 promoter methylation, as well as three out of eight BRAFp.V600E stromal fractions (38%)." (PMID 24244575, 2013). "An interesting network component includes miR-145, the TF MEIS1 (a development and neoplasia gene) and the REV3L gene (the catalytic subunit of DNA polymerase zeta, involved in DNA repair and genome stability), all down-regulated in NTM progression." (PMID 23987127, 2013).
tumor (continued). "One of the tumor fractions showed MEIS1 methylation, the other fraction was unmethylated for MEIS1 and also the entire normal stromal fraction showed MEIS1 promoter methylation." (PMID 24244575, 2013). "Tumors were tested for MEIS1 promoter methylation status (n = 228), MSI status (n = 213), BRAF mutation status (n = 163) and tumor location (n = 168)." (PMID 24244575, 2013). "To determine the origin of MEIS1 promoter methylation in heterogeneous tissue, we studied flow-sorted epithelial tumor cells and normal stromal fractions." (PMID 24244575, 2013). "For tumor TS234t, MEIS1 methylation in the tumor cells was assumed since methylation was detected in the complete tumor only and not in the flow-sorted stromal fraction." (PMID 24244575, 2013). "BRAFp.V600E tumors unequivocally showed elevated MEIS1 methylation levels when compared to BRAF wild types which showed an approximately equal extent of methylation in both tumor and paired normal colon tissue." (PMID 24244575, 2013). "Lower associations were found between MSI-H and MEIS1 promoter methylation (OR = 6.9, CI = 2.4 - 19.7, P = 0.0003), and between tumor location and MEIS1 promoter methylation (OR = 2.4, CI = 1.1 - 5.4, P = 0.028)." (PMID 24244575, 2013). "The MEIS1 promoter methylation status was determined by MSP, and analyzed in relation to BRAF mutation status, MSI status, and tumor location." (PMID 24244575, 2013). "In line with the decreased expression of full length MEIS1, MEIS1D27 expression was unequivocally decreased in five BRAFp.V600E patients with MEIS1 promoter methylation relative to the paired normal tissue, and in one tumor with unmethylated MEIS1." (PMID 24244575, 2013). "In total, four out of eight BRAFp.V600E tumor epithelial fractions (50%) showed MEIS1 promoter methylation." (PMID 24244575, 2013). "However, our results identify several transcription factors, such as MEIS1/2, that are active in both neuroepithelial-like tumor cells and tumor-derived reactive glia, and which seem to be specific to tumor cells." (PMID 35803925, 2022). "Indeed, the Pbx-interacting regions (HR1 and HR2 domains) are required in both the oncogenic function of Meis1 and in the tumor-suppressive role of Prep1, i.e., both activities are performed by a complex of either protein with Pbx1." (PMID 34698191, 2021). "In addition, MEIS1 seems to function as a tumor suppressor in the progression of clear-cell renal cell carcinoma, and similarly in lung cancer." (PMID 34698191, 2021). "MEIS1 also plays a role in solid tumors; however, in this case the MEIS1 role is contradictory as it may behave as an oncogene or a tumor suppressor." (PMID 34698191, 2021). "Moreover, IGF1 has been described as a growth-regulatory MLL-ENL/Hoxa9/Meis1 target and as a direct C/EBPβ target gene involved in autocrine stimulation of transformed murine monocytes and in neoplasia." (PMID 33144337, 2021). "Meis1 overexpression induces tumor formation in Prep1-silenced mouse embryonic fibroblasts." (PMID 33402862, 2020). "Having established the tumor-suppressive capability of MEIS1 and its ability to act as a putative HOXB13 cofactor in PrECs, we next sought to test whether MEIS-mediated growth suppression is HOXB13-dependent." (PMID 32553107, 2020). "Meis1 transcriptionally regulates the expression of hypoxic tumor markers, Hif-1α and Hif-2α." (PMID 32409701, 2020). "This is unlikely, however, given the phenocopied tumor suppression phenotype, high degree of homology between MEIS1 and MEIS2 (72.12% similarity), and previously published data demonstrating that knockdown of both MEIS1 and MEIS2 is required for increased PrCa cell line aggression in vivo." (PMID 32553107, 2020). "Moreover, the expression of Meis1 was found to be inversely correlated with Sox2 expression in ESCC tumor samples." (PMID 33402862, 2020). "Moreover, while Meis1, Meis2, and Pbx1 expressions are downregulated, Hoxa9 expression is upregulated during the tumor initiation and progression of PC." (PMID 33402862, 2020).
tumor (continued). "In PC, the high expression of Meis1 and Meis2 is required for the growth of the tumor." (PMID 33402862, 2020). "These correlative findings provide support to a tumor-suppressive role for MEIS1 and MEIS2 in PrCa." (PMID 32553107, 2020). "In addition, the 2-stage skin carcinogenesis mouse model has shown that Meis1 has a protumorigenic (oncogenic) function in the development of tumor and malign transformation." (PMID 33402862, 2020). "HOXB13 deletion demonstrates that the tumor-suppressive activity of MEIS1 is dependent on HOXB13." (PMID 32553107, 2020). "Additionally, expression profiles and survival analyses revealed that MEIS1 level was significantly downregulated in tumor tissue relative to solid tissue normal (P < 0.001), with decreased MEIS1 level associated with worse PFS (HR < 0.55, P = 0.005) in mCRC." (PMID 33585439, 2020). "Thus, modulation of OCT4 and SOX2 protein expression occur via differentiation signals, and MEIS1 is contributed in this modulation of tumor cell differentiation." (PMID 31090196, 2019). "In addition, an inverse association between MEIS1 and SRY (sex determining region Y)‐box 2 (SOX2) in ESCC tumor samples was reported." (PMID 31090196, 2019). "Importantly, silencing of MEIS1 significantly inhibited xenograft tumor growth, corroborating the in vitro results." (PMID 30496486, 2019). "Moreover, APCDD1, another super-enhancer-associated gene, acting as a downstream target of both MEIS1 and EWS-FLI1, is also characterized as a novel tumor-promoting factor in this malignancy." (PMID 30496486, 2019). "Overexpression of MEIS-1 enhanced the anti-tumor effect of RFA." (PMID 29632641, 2018). "Moreover, in rodent HCC model we found overexpression of MEIS-1 enhanced the anti-tumor effect of RFA treatment." (PMID 29632641, 2018). "Previously, MEIS-1 was reported as a positive tumor inducer." (PMID 29632641, 2018). "To validate whether MEIS-1 intrinsicly expression affects tumor growth, we next established HCC cell lines with low or high MEIS-1 expression level." (PMID 29632641, 2018). "High level of MEIS1 was detected in non-tumor cell line, HEK-293 and HKC." (PMID 28270206, 2017). "First, the endogenous level of MEIS1 in ccRCC and non-tumor kidney cells was examined by WB." (PMID 28270206, 2017). "MEIS1 exhibits a decreased expression in ccRCC cell lines than that in non-tumor cell lines." (PMID 28270206, 2017). "This work discovers, for the first time, MEIS1 as a tumor suppressor in ccRCC." (PMID 28270206, 2017). "Finally by integrating ChIP-seq and RNA-seq data from the various cell lines we identify a tumor-specific Meis1 signature and a suppression-specific Prep1 signature." (PMID 26259236, 2015). "Furthermore, our investigations of the role of Meis1 in tumorigenesis revealed an unexpected switch of Meis1 localization from a stem cell region in normal epidermal tissues to a more differentiated region in tumor tissues." (PMID 25013928, 2014). "The decreased expression of MEIS1 was also observed for prostate poor-prognosis tumors, suggesting that MEIS1 might act as a tumor suppressor in human prostate cancer." (PMID 25186767, 2014). "Furthermore, three out of eight BRAFp.V600E tumor stromal fractions showed MEIS1 promoter methylation (38%)." (PMID 24244575, 2013). "The association between BRAFp.V600E and MEIS1 promoter methylation was validated in a larger, consecutive cohort and both significant when considering BRAFp.V600E as a single factor and after correction for MSI and right-sided tumor location." (PMID 24244575, 2013). "Associations between MEIS1 promoter methylation and BRAF mutation status, MSI and tumor location." (PMID 24244575, 2013). "In addition, also the normal stromal cells from these tumors, which consisted of tumor infiltrating lymphocytes and fibroblast-like cells, showed MEIS1 promoter methylation." (PMID 24244575, 2013).
tumor (continued). "Univariate analysis, which considers individual variables contributing to MEIS1 promoter methylation (BRAF mutation status, MSI status, and tumor location), showed that BRAFp.V600E had the highest association with MEIS1 promoter methylation (OR = 13.0, CI = 5.2 - 33.0, P = 0.0001)." (PMID 24244575, 2013). "Based on GO analysis, MEIS1 may take part in tumor development by regulating cell differentiation and “DNA-binding transcription activator and repressor activity”, “RNA polymerase II-specific”, “enhancer sequence-specific” and “activating transcription factor binding”." (PMID 36836180, 2023). "However, as a miRNA generally has many target genes, whether other targets, such as FAM83D, HOXC6 and PBX3 and MEIS1 we mentioned, are involved in miR-495-mediated anti-tumor activity in NPC is still needed to be clarified." (PMID 35301291, 2022). "Thus, both Meis1 oncogenic and Prep1 tumor-suppressing activities require interaction with Pbx1." (PMID 34698191, 2021). "On the other hand, Meis1 and Prep1 compete in mouse tumorigenesis and leukemogenesis because Meis1 acts as an oncogene only in the absence of Prep1 (or other tumor-suppressing genes), and the overexpression of Prep1 in Meis1-dependent tumor cells blocks their growth." (PMID 34698191, 2021). "Overexpression of Meis1 and Meis2 could induce tumor progression." (PMID 33402862, 2020). "In addition, in vivo silencing of Meis1 remarkably suppresses xenograft tumor growth." (PMID 33402862, 2020). "Furthermore, the expression patterns of MEIS1 and stemness marker SALL4 were significantly associated to each other depending on different pathological features of the patients, specifically in early stages of tumor progression." (PMID 32819319, 2020). "Thus, overexpression of MEIS-1 enhances the anti-tumor effect of RFA treatment." (PMID 29632641, 2018). "Thus, overexpression of MEIS-1 enhanced the anti-tumor effect of RFA treatment in in situ HCC." (PMID 29632641, 2018). "For the first time, our study discovers that MEIS1 may function as a tumor suppressor in ccRCC." (PMID 28270206, 2017). "Interestingly, we found that Meis1 localization was altered to neoplasia development." (PMID 25013928, 2014). "A strategy of tumor cells for survival could be down-regulation of MEIS1." (PMID 22185299, 2011). "In contrast, MEIS1 inhibits TGFBR2 expression probably in both normal pro-B-cells and tumour cells of the corresponding BCP-ALL subtype." (PMID 41153416, 2025). "miR-204-5p is an additional well-documented tumor suppressor, which affects PCa growth by controlling the expression of the Homeobox A10 (HOXA10) and Meis Homeobox 1 (MEIS1), as well as the anti-apoptotic gene BCL2." (PMID 36608541, 2023). "A previous study reported that MEIS1 promoted the migration and chemotaxis of CD8 + T cells in OC, while RP5-991G20.1 was significantly downregulated within the tumor tissue of OC." (PMID 37674251, 2023). "HOXA9 and MEIS1 homeobox oncogenes (adjacent and coexpressed with miR-196b), along with FAS tumor suppressor, are direct targets of miR-196b and drive carcinogenesis in KMT2A-r cases in a bidirectional manner." (PMID 36010971, 2022). "MEIS1 impaired CRC cell viabilities and tumor growth in mice and enhanced CRC cell sensitivity to oxaliplatin by preventing DNA damage repair." (PMID 35351858, 2022). "In this study, we describe that MEIS1—cooperatively with HOXB13—is responsible for maintaining expression of secreted, tumor-suppressive proteoglycans such as DCN." (PMID 32553107, 2020). "The resulting 157 DEGs represent genes that are direct targets of MEIS1 only when HOXB13 is present and therefore represent prioritized candidates to elucidate the mechanism of MEIS1-dependent tumor suppression." (PMID 32553107, 2020). "Specifically, they reported a step-wise decrease in MEIS1 expression during PCa progression, but that knockdown of both MEIS1 and MEIS2 were necessary to suppress tumor development in vivo." (PMID 32681068, 2020).